ELF5 (E74 like ETS transcription factor 5)
Diseases named in the same sentence as ELF5 in open-access papers (continued):
Sharing a sentence is not in itself a finding about the gene and the disease.
tumor (34 papers, 2007 to 2025). "The putative targets of miR-223-3p included the gene encoding ELF-5, which has been reported to possess tumor-suppressive properties in many types of cancer by inhibiting cancer cell proliferation, migration and invasion." (PMID 39428471, 2024). "We were also able to induce the expression of the E74-like factor 5 (ELF5), a tumor suppressor in RCC, in the 786-0, VHL deficient, RCC cell line under hyperosmotic cell culture conditions." (PMID 32059438, 2020). "In contrast, methylated tumor tissues showed a significant loss of Elf5 mRNA expression (median: 0.33, P<0.01)." (PMID 25629735, 2015). "We show that induction of ELF5 in the PyMT model leads to an increase in lung metastasis because ELF5 recruits MDSCs to the tumor, which promotes leaky vasculature and causes an increase in lung metastasis." (PMID 26717410, 2015). "Results revealed that low expression of Elf5 on protein and mRNA levels were associated with tumor progression, early relapse and poor survival." (PMID 25629735, 2015). "TEAD4, TBP, MYC, and ELF5 constituted the transcription factor regulatory network of C2 CPE+ tumor cells." (PMID 40230840, 2025). "The tumor volume and weight were also obviously lower in the ELF5-overexpressed mice, while the tumor volume and weight in the ELF-ΔSET treated group were not significantly different from those in the control group." (PMID 37980532, 2023). "Bioinformatics tools showed that ELF5 expressed at a low expression in tumor stages, tumor grades, lymph node metastasis, and subtypes of KIRC." (PMID 37980532, 2023). "The regulation of ELF5 in vitro encouraged us to explore further the impact of ELF5 on RCC tumor growth." (PMID 37980532, 2023). "ELF5 acts as a tumor suppressor though activating the transcription of USP3 to stabilizing WDTC1 in RCC." (PMID 37980532, 2023). "Survival analysis further showed that, under the same tumor grade, high expression of ELF5 predicted better prognosis, while low expression of ELF5 had poorer prognosis." (PMID 37980532, 2023). "Expression of COMMD3 in luminal-A-like tumours was directly associated with markers of luminal differentiation: c-KIT, ELF5, androgen receptor and tubule formation (the extent of normal glandular architecture; p < 0.05)." (PMID 37072858, 2023). "We also confirmed that the expression of ELF5 was upregulated in the mouse tumor tissues in the 5-Aza-dC group compared with the control group." (PMID 37980532, 2023). "The 5-Aza-dC treatment was also demonstrated to inhibit mouse tumor growth and upregulate ELF5 expression in tumor tissues, which showed the therapeutic potential in RCC by regulating ELF5." (PMID 37980532, 2023). "5-Aza-dC as a DNA methyltransferase inhibitor showed the potential for RCC tumor suppression via ELF5." (PMID 37980532, 2023). "We do note, however, that the tumours in our study as well as human TNBCs express transcriptional regulators of alveologenesis such as Elf5, Sox10, Foxc1 and Cebpb." (PMID 33686070, 2021). "MCF7 cells stably transfected with ELF5-WT, ELF5-6KR, ELF5-6KQ, or the control vector were inoculated into the flanks of nude mice to perform the xenograft assay to further test the tumor suppressing role of ELF5 acetylation." (PMID 33742100, 2021). "We found 2 cases of endocrine-resistant brain metastases where ELF5 levels were greatly increased and ELF5 patterns of gene expression were enriched, compared to the matched primary tumour." (PMID 31895944, 2020). "This tumour collection contained 7 ER+ cases, 2 of which, X4 and X72, showed a large increase in ELF5 expression in the metastasis compared to the matched primary." (PMID 31895944, 2020). "We found an increase in ELF5 levels, and enrichment of the ELF5 transcriptional signature, in the endocrine resistant brain metastases of ER+ primary tumours." (PMID 31895944, 2020).
tumor (continued). "In vivo, reduced ELF5 expression can promote tumor growth and induce the most probability of distant metastasis in mice bearing LNCaP xenograft tumors receiving enzalutamide treatment." (PMID 28287091, 2017). "Our further experiment about validation and clinicopathologic analysis revealed that high expression of CXCL3, ELF5, and TIMP1 was significantly associated with lymphatic invasion, distance metastasis, and advanced tumor stage." (PMID 29209625, 2017). "More importantly, high expression of CXCL3, ELF5, and TIMP1 was significantly associated with lymphatic invasion, distance metastasis, and advanced tumor stage." (PMID 29209625, 2017). "ELF5 was originally described as a tumor suppressor; however, the role of this protein in cancer is complex and context-dependent." (PMID 26738740, 2016). "Injection of primary cells into the tail vein of wild-type hosts produced engraftment of WT tumor cells in the lungs, but rarely when the cells expressed ELF5." (PMID 26717410, 2015). "Myeloid-derived suppressor cells, a group of immature neutrophils recently identified as mediators of vasculogenesis and metastasis, were recruited to the tumor in response to ELF5." (PMID 26717410, 2015). "Induction of ELF5 greatly increased the amount of PyMT-mRNA present in blood, suggesting increased numbers of circulating tumor cells." (PMID 26717410, 2015). "ROS production by MDSC was significantly increased in both infiltrated granulocytic and monocytic subsets in response to Elf5, consistent with a tumor permissive environment." (PMID 26717410, 2015). "ELF5 reduced the motility of tumor cells through a permeable membrane in a Boyden chamber, using serum as the chemo-attractant, and also reduced the ability of these cells to invade through a layer of matrigel using the same apparatus." (PMID 26717410, 2015). "High cytoplasmic ELF5 expression in luminal patients also correlated with a pro-tumor inflammation characterized by decreased cytotoxic T-CD8 lymphocytes." (PMID 26717410, 2015). "Tumor samples showed a decrease in Elf5 levels within a range of 0.03 to 2.02-fold in comparison to the same control as normal tissues, with a median of 0.40-fold lower expression." (PMID 25629735, 2015). "We also observed that the antibody treatment reduced the number of red blood cells within the primary tumor, establishing MDSCs as a key part of the mechanism responsible for both induction of metastases and the hemorrhagic tumor phenotype by ELF5." (PMID 26717410, 2015). "We used these flow-sorted primary cells to examine other cell-autonomous aspects of ELF5 action in tumor formation." (PMID 26717410, 2015). "Upregulated ELF5 ChIP targets were characterized by the presence of tumor suppressor genes while downregulated genes were enriched in genes controlling cell proliferation." (PMID 23300383, 2012). "Precancerous clusters showed enrichment in tumor progression-related regulons, including transcription factors (TFs) linked to tumor proliferation and cell cycle progression (STAT1, BCL6, ETV5) and potential tumor suppressors (ELF5, LTF, RXRG, CEBPD), as well as EMT-related regulons." (PMID 39872221, 2025). "The potential tumor suppressor ELF5 was found only in precancerous clusters." (PMID 39872221, 2025). "ELF5 functions as a tumor suppressor in bladder, kidney, ovary, and prostate cancers." (PMID 38275872, 2024). "The mouse model was established for further examining ELF5 function on tumor growth in vivo." (PMID 37980532, 2023). "Interestingly, COMMD3 was significantly associated with markers of luminal differentiation and/or fate commitment in the luminal A-like tumours: tubule formation, androgen receptor (AR), ELF5 and cKIT (Fig-2I)." (PMID 37072858, 2023). "The tumor growth in mice was inhibited by ELF5 overexpression." (PMID 37980532, 2023). "Similarly, we further found that ELF5 upregulation notably suppressed MVD in tumor tissues, instead of ELF-ΔSET." (PMID 37980532, 2023).
tumor (continued). "Collectively, ELF5 overexpression repressed tumor growth and angiogenesis in vivo." (PMID 37980532, 2023). "In addition, in KIRC samples, we found that ELF5 was significantly low expressed in cancer stages, tumor grades, lymph node metastasis and subtypes." (PMID 37980532, 2023). "Furthermore, the cells that expressed ELF5-6KQ displayed a slower tumor growth rate and a smaller tumor volume than the control cells, similar to the cells that expressed ELF5-WT." (PMID 33742100, 2021). "Lower Cyclin D1 level was found to correspond to higher ELF5 expression in tumor tissues." (PMID 33742100, 2021). "This indicates that ELF5 can act as a tumor suppressor in ccRCC." (PMID 32059438, 2020). "Besides that, high CXCL3 and ELF5 expression was also significantly related to vascular invasion, and low PHLPP2 expression was significantly associated with vascular invasion and tumor stage." (PMID 29209625, 2017). "Higher ELF5 expression may result in the tumor being seen by the host as an involuting mammary gland, and the luminal A subgroup may possess a background phenotype which allows or best expresses this appearance." (PMID 26717410, 2015). "Increasing evidences suggest that anomalous EMT development triggers malignant tumor progression while Elf5 may have an inhibitory role in this process." (PMID 25629735, 2015). "Then, the Elf5 expression was quantified according to tumor stages." (PMID 25629735, 2015). "In the case of tumor specific up-regulated genes the predicted composite module comprised of Myc, Elf5 and Cebpα binding sites found in 20 (74%), 26 (96%) and 25 (93%) genes, respectively while the entire composite module fitted 17 promoters or 63% of up-regulated genes." (PMID 26427040, 2015). "Interestingly this effect swamps the cell autonomous effects of ELF5, which predict a tumor suppressor action." (PMID 26717410, 2015). "We showed that Elf5 expression was negatively correlated with tumor grade and stage." (PMID 25629735, 2015). "In this study, we have discovered that ELF5 drives the spread of tumor cells to the lungs." (PMID 26717410, 2015). "Interestingly, this effect is able to overcome the other tumor-suppressive effects of ELF5 on cancer cells, such as reduced proliferation, motility, and invasion." (PMID 26717410, 2015). "While the importance of Elf5 in normal mammary gland development is firmly established, whether it acts as a tumor suppressor or an oncogene in breast tumorigenesis remains to be determined." (PMID 20831799, 2010). "Thus, DNA methylation may also explain the role of low-expressed ELF5 in the regulation of tumor activity in RCC." (PMID 37980532, 2023). "ELF5 is an epithelial-specific member of the Ets transcription factor family and regulates a variety of cellular biological processes including keratinocyte terminal differentiation, trophoblast differentiation, and epithelial–mesenchymal transformation in tumor cells." (PMID 34055778, 2021). "Thus, according to our data, CCND1 could be a target gene of ELF5, indicating that the execution of a tumor suppressor via CCND1 may be another action mechanism of ELF5." (PMID 33742100, 2021). "Thus Elf5 increased the number and suppressive ability of tumor-infiltrated MDSC." (PMID 26717410, 2015). "In the MMTV-PyMT model, ELF5 contributes to tumor progression; this discrepancy might be as a result of the poor modeling of the distal stroma in the PyMT tumor FACS analysis, where the majority of the tissue analyzed corresponds to intratumoral and adjacent stroma." (PMID 26717410, 2015). "Significant downregulation of ELF5 was observed in paired COAD samples, suggesting its potential role as a tumor suppressor in this cancer type." (PMID 39697539, 2024). "E74-like ETS transcription factor 5 (ELF5) is involved in a wide spectrum of biological processes, e.g., mammogenesis and tumor progression." (PMID 33742100, 2021).
tumor (continued). "The ETS transcription factor Elf5 (E74-like factor 5) is a target of the prolactin-STAT5 axis and promotes mammary cell differentiation, supporting the tumor suppressive role of STAT5 in the mammary gland." (PMID 31557897, 2019). "Genes encoding proteins involved in ion and electron transport (CYB5R2, GABRP), and genes encoding proteins with transcription factor and regulator activity (ELF5, ID4) were downregulated in both populations of tumor cells." (PMID 17389037, 2007). "ELF5 upregulation notably repressed RCC cell proliferation, migration, invasion, and tumor growth." (PMID 37980532, 2023). "We further assessed ELF5 expression in RCC and discovered ELF5 expressed at a low level in tumor tissues of RCC patients compared to non-tumoral tissues." (PMID 37980532, 2023). "IHC results manifested that Ki67 and VEGFA expression in tumor tissues was decreased via ELF5 but not ELF-ΔSET overexpression." (PMID 37980532, 2023). "The inhibitory effect of ELF5 on tumor proliferation was abolished in a CCND1 rescue experiment or by overexpression of Cyclin D1, suggesting that the function of ELF5 might be CCND1-dependent." (PMID 33742100, 2021). "For example, the expression of the E74 like ETS transcription factor 5 is not detectable in ccRCC samples and ectopic ELF5 expression reduced tumor development in mice." (PMID 32059438, 2020). "We observed that much higher rates of cell proliferation occurred in the areas of the tumor which expressed low levels of ELF5, marked by low or no EGFP." (PMID 26717410, 2015). "Compared with these NU tissues, unmethylated UC showed an almost equal Elf5 expression without considering tumor stage or grade (median: 0.80, P = 0.08)." (PMID 25629735, 2015). "To overcome the effects of heterogeneous ELF5 induction, we performed intraductal allografts of Fluorescence-Activated Cell Sorting (FACS)-sorted (Lin- and CD24+) tumor cells that were either EGFP (ELF5) positive or negative." (PMID 26717410, 2015). "Notwithstanding the lack of a clear-cut role of Elf5 in tumor development, it is safe to posit that this transcription factor is an important mediator of various facets of mammary gland biology and warrants further experimental studies." (PMID 20831799, 2010). "Importantly, ELF5 mRNA and protein have been confirmed to be decreased in RCC, and re-expression of ELF5 can suppress cell proliferation and survival, which indicates that ELF5 has tumor suppressive activity in the kidney." (PMID 37980532, 2023). "Altogether, overexpression of ELF5-ΔSET remained unchanged as compared to control and exhibited no change in tumor growth and angiogenesis of RCC whereas WT ELF5 overexpression resulted in decreased tumor progression suggesting the crucial role of ELF5 in suppressing RCC tumor." (PMID 37980532, 2023). "Conditions that upregulate ELF5 expression, for example continuous endocrine therapy, or increased exposure to RANKL once resident in bone, may drive phenotypic conversion to an endocrine-resistant state via the remaking of the cell-fate decisions taken by the tumour initiating cells." (PMID 31895944, 2020).
cancer (27 papers, 2010 to 2025). A tumor composed of atypical neoplastic, often pleomorphic cells that invade other tissues. "It discusses the lineage-specific expression of ELF5, its regulatory mechanisms, and its potential as a biomarker for breast-specific biological age and cancer risk." (PMID 38275872, 2024). "Examples of genes with diagnosis-specific interactions include ELF5, which is associated with epithelial cell function and has implications in cancer." (PMID 39399221, 2024). "Examination of publicly accessible genomic data reveals mutations in ELF5 are relatively rare in human cancers." (PMID 30200227, 2018). "In other tissues, cancer was associated with an aberrant increase in ELF5 expression, as seen in the cervix, colon, rectum, and uterus." (PMID 26738740, 2016). "In addition to the transcription factor E74-like factor 5 (Elf5), we observed up-regulation of planarian orthologs of other developmental or cancer associated genes." (PMID 30194301, 2018). "To learn how the loss of ELF5 in cancer cells supports its viability, we assessed proliferation and apoptosis markers in both stably selected LNCaP and VCaP cells infected by shELF5 (LNCaP-shELF5 or VCaP-shELF5) or scramble shRNA (shScr) (LNCaP-shScr or VCaP-shScr)." (PMID 28287091, 2017). "This may indicate an oncogenic role for ELF5 in these tissues or broader genomic deregulation, such as DNA hypomethylation, a hallmark of the cancer genome." (PMID 26738740, 2016). "Aging changes, like reduced ELF5 and increased DNA modifications, may contribute to cancer risk." (PMID 38275872, 2024). "ELF5 expression undergoes significant changes across various cancers when compared to normal tissues." (PMID 38275872, 2024). "In BC, ELF5 expression patterns are subtype specific and it exhibits bifunctional roles of promoting or suppressing cancers in a subtype-dependent manner." (PMID 38275872, 2024). "We identified 30 cancer-specific normal-invariant genes, including Zic family members (ZIC1, ZIC4, and ZIC5), DPPA2, PRSS56, ELF5, and FGF18, most of which were cancer-associated genes." (PMID 39969322, 2024). "The Cancer Genome Atlas data analysis reveals generally low ELF5 expression in luminal A/B BCs, with exceptions of higher expression in some cases." (PMID 38275872, 2024). "In cancer, ELF5 acts differently in various subtypes, affecting cell growth and hormone sensitivity." (PMID 38275872, 2024). "Although the roles of genes like ARRDC5 and ELF5 in cancer progression have been studied, their pan-cancer significance across different cancer types has not been fully demonstrated." (PMID 39697539, 2024). "Several genes, including ARRDC5, ELF5, FIBCD1, LINC00494, NLRP7, and L1CAM, have been implicated in various aspects of cancer progression and metastasis." (PMID 39697539, 2024). "This review focuses on the role of ELF5 in normal breast development, its altered expression throughout aging, and its implications in cancer." (PMID 38275872, 2024). "Pan-cancer analysis indicated that ELF5 expression was downregulated in most cancers and was an extensive cancer suppressive factor potentially." (PMID 37980532, 2023). "Several studies have demonstrated that ELF5 is lowly expressed in human cancers and acts as an oncogene regulator, including RCC." (PMID 37980532, 2023). "E74-like transcription factor 5 (ELF5) has been verified to participate in the progression of different cancers and can regulate angiogenesis." (PMID 37980532, 2023). "Most evidence suggests that ELF5 exerts the vital function in inhibiting tumorigenesis and development in different human cancers." (PMID 37980532, 2023). "As expected, we also found more cell fraction in G2M stage after enzalutamide treatment in ELF5-downregulated cancer cells." (PMID 28287091, 2017).